CD163 (CD163 molecule)
Diseases named in the same sentence as CD163 in open-access papers (continued):
Sharing a sentence is not in itself a finding about the gene and the disease.
metastatic disease (19 papers, 2016 to 2026). "In this study, these groups were associated with different clinical outcomes, and CD68/CD163/CD209-immune hotspots predicted progression to metastatic disease and cancer-specific survival." (PMID 37190147, 2023). "We used immunohistochemistry to analyze the expression of PD-1, PD-L1, indoleamine-pyrrole 2,3-dioxygenase (IDO), and CD163 (a marker of tumor-associated macrophages [TAMs]) in metastatic tumors." (PMID 34797860, 2021). "TAMs with double positivity for CD68 and CD163 are more likely to be found in lymph node metastatic tumors in the tumor microenvironment." (PMID 41256322, 2025). "There were higher immune cell infiltrations of CD3 (lymphocytes), CD103 (resident memory lymphocytes), and CD163 (M2 macrophages) positive cells in the primary compared to metastatic tumors." (PMID 38691575, 2024). "In our cohort, CD68/CD163/CD209-immune hotspots predicted progression to metastatic disease and cancer-specific survival." (PMID 37190147, 2023). "Similarly, in clinical samples, the protein expression of the M2 macrophage marker CD163 was significantly higher in lung metastatic tumors compared to primary tumors." (PMID 38605400, 2024). "Likewise, tissue samples from patients with either localised or metastatic osteosarcoma have shown a higher infiltration of CD163 macrophages in patients with metastatic disease than in patients with localised disease." (PMID 36900335, 2023). "Additionally, necrotic lesions and anti‐inflammatory CD163‐expressing cells were more frequent in pulmonary metastatic tumours in this group." (PMID 37649158, 2023). "In addition, immunohistochemistry and multiplex immunofluorescent staining confirmed that the ratio of CD163/CD68-positive cells was significantly increased in the liver metastatic tumor (p = 0.0313), suggesting the crucial role of M2 macrophage infiltration in the pathogenesis of HPD." (PMID 39289546, 2024). "Immunohistochemical analysis of subcutaneous tumors and lung metastatic tumors in mice from the sh-METTL3 and sh-NC groups indicated that silencing METTL3 significantly reduced the expression of the M2 macrophage marker CD163 protein." (PMID 38605400, 2024). "In contrast, M2 macrophage markers, including CD206, CD163, and VEGF expressions were higher in metastatic tumors." (PMID 34580284, 2021). "Fifty-nine tumor samples from patients with pathologically confirmed squamous cell carcinoma of the larynx, stage I–IV non-metastatic disease, who were treated at the University Hospital of Split, were immunohistochemically stained for the expression of STING, cGAS, CD8, CD68, and CD163." (PMID 37444620, 2023). "Furthermore, the density of HO-1+ cells in TINT increased with tumor aggressiveness, suggesting that fast-growing and metastatic tumors attract more HO-1+ macrophages (as well as CD68+ and CD163+ macrophages ) to the tumor-bearing organ than slow-growing and non-metastatic tumor variants." (PMID 27280718, 2016).
rheumatoid arthritis (19 papers, 2011 to 2025). A chronic, systemic autoimmune disorder characterized by inflammation in the synovial membranes and articular surfaces. "CD163, a classical marker of regulatory macrophages, is highly expressed in spondylarthritis compared to rheumatoid arthritis and associated with inflammation." (PMID 37283752, 2023). "The CAIA model, which is a more simple and largely T cell-independent model of rheumatoid arthritis, was used to further address the effect of CD163 deficiency during inflammatory disease." (PMID 32710083, 2020). "In rheumatoid arthritis, psoriasis, atopic dermatitis (AD), and rosacea, CD163 levels have been shown to be elevated." (PMID 38321132, 2024). "CD68/CD163+ synoviocytes were preferentially located in the vicinity of the synovial lining layer of rheumatoid arthritis patients while they were randomly distributed in PVNS." (PMID 21899757, 2011). "Taking clues from other inflammatory diseases of the joint such as rheumatoid arthritis (RA) and osteoarthritis (OA), infiltration of CD206+, FRβ+, CD163+, MMP-9+ and iNOS+ macrophages has been reported." (PMID 35733858, 2022). "However, expression of CD163 on infiltrating inflammatory macrophages in mouse models of rheumatoid arthritis has not yet been described." (PMID 32710083, 2020). "More recent studies using healthy and rheumatoid arthritis (RA) synovium have proposed new nomenclature for different synovial macrophage subsets, including CX3CR1+/TREM2+ lining macrophages and subsets based on the expression of CD163, CD206, and MERTK." (PMID 37612718, 2023).
Granuloma (18 papers, 2012 to 2025). A compact, organized collection of mature mononuclear phagocytes, which may be but is not necessarily accompanied by accessory features such as necrosis. "The characterization of the granulomas associated to degenerated flukes revealed a high number of type 2 macrophages (CD163+) and CD3+ T lymphocytes with a low population of Foxp3+ Treg cells." (PMID 34679889, 2021). "In granulomas from animals with active disease, or 2 months of drug treatment, there is a weak but significant association between pSMAD-2/3 and CD163." (PMID 27148404, 2016). "In NTMD and TB, CD68 and CD206 were primarily expressed by granuloma epithelioid macrophages, while CD163 was expressed by interstitial scattered macrophages." (PMID 41189710, 2025). "In granulomatous skin disease, FBP1 expression was detected in CD68-positive granuloma regions, while CD163 was observed surrounding FBP1-positive regions." (PMID 38038136, 2023). "CD68+ granulomas with well-defined borders were less frequent in TB/HIV–co-infected lymph nodes and CD68+ cells were confined inside the M. tuberculosis granulomas, whereas CD163+ cells were located at the periphery, surrounding CD68+ macrophage clusters." (PMID 35092727, 2022). "Inconceivably, ECs from TT granulomas exhibited the M1 phenotype (CD68+ CD163−), whereas Mφs in LL granulomas showed the M2 phenotype (CD68+ CD163+)." (PMID 34899703, 2021). "Monocytes and CD163+ M2 macrophage were abundant and their distribution in M(n)-type granulomas was like those in M-type granulomas." (PMID 35003119, 2021). "In macaque and human granulomas, proinflammatory macrophage expressing CD163, CD68, HAM56, and iNOS are observed predominantly in the inner region of the lesions granulomas." (PMID 32544188, 2020). "Epithelioid macrophages exhibiting M1 phenotype (CD68+CD163-) predominantly present in granulomas of TT patients, whereas macrophages in LL granulomas are foamy and mainly exhibit the M2 phenotype (CD68+CD163+)." (PMID 32373110, 2020). "We quantified median pixel intensity (MPI) from a collection of granulomas to elucidate how latent and active TGFβ, αSMA, pSMAD2/3, collagen, and CD163 expression change over the three time points we are examining." (PMID 27148404, 2016). "Macrophage features observed in our in vitro human granuloma model strongly align with this theory, including a significant increase in >50 different M2-like macrophage gene transcripts and elevated expression of CD163 in sarcoidosis granulomas at the protein level." (PMID 32849608, 2020). "Correlation analysis of positivity rates for CD68, CD86, CD163, and CD206 reveals a significant correlation between CD68 and CD206 in NTMD, primarily expressed in granulomas." (PMID 41189710, 2025). "The granuloma structure characterization found in both patient biopsies was carried out via immunohistochemistry (IHC) using anti-CD68, anti-CD163 and anti-CD3, or anti-CD8 antibodies as markers of the monocyte/macrophage and lymphocyte lineages, respectively." (PMID 38067175, 2023). "Our data revealed that granulomas were mainly composed of CD68 and, to a lesser extent, of CD163 monocytes/macrophages and of CD3 T-lymphocytes." (PMID 38067175, 2023). "We found that caseous granulomas from animals with active, untreated disease contained strongly staining fibrils of collagen I that could be visualized in the central region of the lesion while pSMAD-2/3+ and CD163+ cells were present along the periphery of the structure." (PMID 27148404, 2016). "Many S-100+, CD68+, CD163+, CD204+, Fascin+, HLA-DR+, and T cells were found in and around granulomas." (PMID 22588497, 2012). "A diverse array of innate immune cells, including mast cells (MC) (cluster 20: HDC, CPA3, KIT), dendritic cells (DC) (cluster 23: CLNK, WDFY4, FLT3), neutrophils (FCGR3B, FFAR2, CSF3R), and macrophages (CD68, CD163, C1QA/B/C), was also present in these granulomas." (PMID 40772762, 2025).
Granuloma (continued). "However in CVID, reduced expression of the fibrosis-related protein fibronectin, but enrichment of CD163, CD3 and FAPα inside CVID granulomas was observed." (PMID 39373788, 2024). "As in granulomas, immunoregulatory genes such as PD-L1, IDO1 and CD163 were upregulated in blood." (PMID 35058616, 2022). "Histologic examination of a pre-therapy lymph node biopsy specimen revealed non-caseating granulomas with sheets of CD1A−/CD207−/fascin+/CD163+/factorXIII−/PGM1+ histiocytes." (PMID 28512266, 2017). "Many S-100+, CD68+, CD163+, CD204+, Fascin+, and T cells were found in and around granulomas." (PMID 22588497, 2012). "The granulomas within NTMD predominantly express CD68 and CD206, contrasting with the CD163 expression found in non-granulomatous areas, indicating distinct subpopulations with different roles." (PMID 41189710, 2025).
HIV-1 infection (18 papers, 2011 to 2024). The type species of lentivirus and the etiologic agent of acquired immunodeficiency syndrome (AIDS). "Upregulated C1QA, CD163, and CXCL16 and downregulated LMNA and CLU were identified as age-associated genes tied to HIV-1 infection." (PMID 38399364, 2024). "The isolated immune cells were exposed to the same HIV conditions as the tissue biopsies and we assessed HIV-1 infection in DC, CD163+ macrophages and CD4+ T cells, which should represent the immune cells susceptible to HIV-1 infection." (PMID 32876566, 2020). "Here we investigated CD163 expression on monocyte subsets ex vivo, on cultured macrophages, and soluble in plasma, in the setting of HIV-1 infection." (PMID 21625498, 2011). "This is consistent with increased CD163 levels of expression by the macrophages in HIV-1 infection." (PMID 32391124, 2020). "As we described and observed before and herein, cmMTB-treated cells were positive for the M(IL-10) markers (CD16+CD163+MerTK+ and phosphorylated STAT3), and displayed a high rate of HIV-1 infection, as compared to those treated with cmCTR." (PMID 32223897, 2020). "In patients with persistent HIV-1 infection during ART, there was a significant decrease in plasmatic sCD163 proportions and intermediate monocyte surface CD163 density, while surface CD163 levels on intermediate monocytes and sCD163 proportions remained higher than in HIV-uninfected individuals." (PMID 35479083, 2022). "We show that CD163 is more highly expressed on CD14++CD16- compared to CD14++CD16+ monocytes, and not expressed on CD14+CD16++ monocytes, at the level of both protein and gene expression, and that expression is increased in HIV-1 infection." (PMID 21625498, 2011). "However, we show that membrane bound CD163 in fact increases and there is no detectable change in sCD163 levels in HIV-1 infection." (PMID 21625498, 2011). "Soluble CD163 in plasma was not significantly altered by HIV-1 infection." (PMID 21625498, 2011). "Further investigation into the effect of chronic bacterial translocation on CD163 expression and shedding in HIV-1 infection, and correlation with other markers of inflammation, may uncover a better understanding of chronic immune activation in HIV-1 infection." (PMID 21625498, 2011).
psoriasis (18 papers, 2012 to 2025). An autoimmune condition characterized by red, well-delineated plaques with silvery scales that are usually on the extensor surfaces and scalp. "Biomarkers such as CD163, expressed on M2 macrophages, are associated with anti‐inflammatory functions and can serve as indicators of immune regulation in inflammatory diseases like psoriasis." (PMID 40539722, 2025). "Biomarkers such as CD163 on M2 macrophages are associated with these anti‐inflammatory functions, serving as potential indicators of disease progression or response to treatment in conditions like psoriasis." (PMID 40539722, 2025). "The phenotype and function of CD163+ macrophages is unclear, as CD163+ macrophages have been associated with wound healing and the resolution of inflammation, but have also been implicated in inflammation, such as in spondyloarthritis, psoriasis and inflammatory bowel disease." (PMID 28800775, 2017). "These markers, particularly CD163, are critical for monitoring macrophage polarization and inflammation in autoimmune conditions like psoriasis, and produce anti‐inflammatory cytokines such as IL‐10, TGF‐β." (PMID 40539722, 2025). "Biomarkers such as CD163, expressed on M2 macrophages, are valuable in assessing disease activity and therapeutic responses in psoriasis." (PMID 40539722, 2025). "The previous study demonstrated that macrophage marker CD68 was increased in psoriasis compared to normal skin, and coexpressed with CD163." (PMID 32411188, 2020). "CD163 is expressed by resident macrophages and chronic inflammatory macrophages found in psoriasis, celiac disease, and Crohn’s disease." (PMID 32453711, 2020). "Numerous CD163+ cells in psoriasis were observed in at least two forms: small-sized cells with a small nucleus, as in lymphocytes, and relatively large branched cells; these varieties persisted after treatment." (PMID 32411188, 2020). "Generally, CD163+ cell quantities in psoriasis-affected skin significantly dominated over CD68+ before and after all treatment regiments." (PMID 32411188, 2020). "Furthermore, immunohistochemistry showed abundant numbers of CD11b+, CD11c+, CD14+, CD163+ and plasmacytoid dendritic cells in early‐phase new‐onset psoriasis." (PMID 40181552, 2025). "Results indicated increased CD163(+) cells and higher serum sCD163 levels in these conditions, suggesting a link to disease severity and their potential as biomarkers for guiding personalized treatment approaches in psoriasis." (PMID 40539722, 2025). "Biomarkers like CD163(+) M2 macrophages are associated with disease progression, while treatments that enhance M2 macrophage function, such as PSORI‐CM02 and Treg‐of‐B cell therapies, show potential in alleviating psoriasis symptoms." (PMID 40539722, 2025). "The expression of CD163, which is a well-known superior dermal macrophage marker, can identify a subpopulation of classically activated macrophages in skin diseases, such as psoriasis." (PMID 33800730, 2021). "In aggregate, these reports suggest that CD163+ M2-polarized macrophages could contribute to the pathogenesis of autoimmune skin diseases such as BP and psoriasis." (PMID 32707850, 2020). "Another study examined CD163(+) cells and soluble CD163 level in Cutaneous T cell Lymphoma (CTCL) and Atopic Dermatitis (AD), and psoriasis‐affected skin." (PMID 40539722, 2025). "In obese psoriasis patients, pioglitazone therapy did not significantly affect CD163+ (M2‐like) macrophage infiltration, indicating that its therapeutic impact is specifically targeted at CD68+ (M1‐like) pro‐inflammatory macrophages." (PMID 40539722, 2025). "On the other hand, the lesional skin of psoriasis possesses heterogeneous CD163+ M2-polarized macrophages, including MARCO+ phenotypes of M2 macrophages, as well as IL-23- or TNFa-producing macrophages that contribute to the Th17-polarized inflammatory microenvironment of psoriasis." (PMID 32707850, 2020).
psoriasis (continued). "Histologically, NL and LS skin biopsies from GEN001 were indistinguishable from classic psoriasis, and contained similar numbers of CD3+ CD11c+ and CD163+ cells (data not shown)." (PMID 25369198, 2014).
co-infection (17 papers, 2014 to 2025). "In vitro, co-infection of susceptible epithelial CD163+ cells with PRRSV and swIAV interfered the replication of each other, while in pigs, some level of interference could also be observed when PRRSV infection preceded swIAV inoculation." (PMID 36337208, 2022). "In detail, apart from a significant upregulation of CD163 compared to both bacterial infection and co-infection, IAV had hardly any impact on the expression of the investigated surface proteins." (PMID 36365071, 2022). "The CD163 function in the co-infection pathogenesis needs further studies." (PMID 25906258, 2015). "Furthermore, during co-infection with Mtb these antigens promoted different types of regulatory macrophages: T. muris antigen increased CD206 expression (M2a-like macrophages) whereas H. diminuta antigen increased CD163 expression (M2c-like macrophages)." (PMID 28192437, 2017). "In vitro co-infection of macrophages led to significantly elevated expression of TLR2 and CD80 compared to bacterial mono-infection, whereas CD163 and CD206 were downregulated." (PMID 36365071, 2022). "In detail, we detected that the immune sensors CD163 and CD206 were markedly downregulated in co-infection compared to only GAS-infected macrophages." (PMID 36365071, 2022). "The downregulation of CD163, as well as the attenuation of the GAS-induced CD206 upregulation in the IAV+GAS group, further supports the notion that a preceding IAV infection led to a distinct immune response in macrophages during co-infection." (PMID 36365071, 2022). "The CD163 upregulation demonstrated that CD163 may have some important roles in inflammatory responses, especially in H1N1-SS2 co-infection." (PMID 25906258, 2015). "Monocyte surface CD163 expression was quantified by flow cytometry, and found to be significantly elevated on the total CD14+ monocyte population among CTN-055 participants regardless of HCV co-infection, as compared to PLWH ref. at both W0 (Adj." (PMID 35371104, 2022).
Cognitive impairment (16 papers, 2015 to 2025). Abnormal cognition is characterized by deficits in thinking, reasoning, or remembering. "Recent microarray analysis of peripheral blood samples from mild cognitive impairment and cognitively normal subjects has also identified CD163 as a critical gene related to WMLs." (PMID 38674030, 2024). "After correction for histopathological grade P-STAT5b, CD163, CD3, and Semaphorin-3A expression were independently associated with cognitive deficits in different domains." (PMID 35148403, 2022). "Previously, we demonstrated that Nef increases the expression of macrophage chemokine CCL2 and macrophage marker CD163 which correlate with cognitive deficits observed in our animal model when compared to controls." (PMID 31829243, 2019). "Among these biomarkers, soluble CD163 (sCD163) levels increase in both CSF and plasma samples, related to the activation of macrophage/microglia and inflammation levels in neurological diseases, supporting its role also as a cognitive impairment biomarker." (PMID 37759493, 2023). "In our dataset, higher levels of haptoglobin were associated with increased levels of CD163 in stable CN individuals but demonstrated a trend of negative association in those showing progression to cognitive impairment." (PMID 32517787, 2020). "Moreover, PLWH with cognitive impairment (GDS ≥ 0.5) had higher plasma CD163 than those who were not impaired in a study of individuals with chronic HIV infection on cART." (PMID 40722775, 2025).